RETN (resistin)
Diseases named in the same sentence as RETN in open-access papers (continued):
Sharing a sentence is not in itself a finding about the gene and the disease.
Insulin resistance (continued). "In contrast, serum resistin concentration seemed to be higher in children from Asian countries than in those from Europe and the USA but resistin had no or only weak associations with markers of insulin resistance." (PMID 25904939, 2015). "The increased level of resistin may be related to the increased fat mass and could be involved in the development of insulin resistance." (PMID 26273680, 2015). "Consecutively, alternative functions apart from insulin resistance and diabetes have been described: Resistin inherits a strong pro-inflammatory potential through induction of the cytokine cascade and vice versa induction of resistin by pro-inflammatory cytokines has also been demonstrated." (PMID 26303896, 2015). "The relationship between resistin and insulin resistance is controversial." (PMID 25904939, 2015). "Resistin, an insulin resistance biomarker, seems to be a key factor in atherosclerosis and as reported recently high glucose stress was able to induce a significant decrease in miR-492 expression, with a consequent upregulation of resistin expression." (PMID 25268390, 2014). "Adipokines, such as leptin, adiponectin, and resistin, may also be involved in the pathogenesis of insulin resistance." (PMID 25202741, 2014). "Using online miRNA target prediction databases (miTargetFinder and Targetscan), we hypothesized that resistin, an important regulator in insulin resistance, atherosclerosis, and cardiovascular disease, was a target of miR-492." (PMID 24526524, 2014). "The researchers concluded that, in contrast to other adipokines, resistin is only weakly associated with body fat and is unlikely to be a major mediator of insulin resistance or the metabolic syndrome in humans." (PMID 24692844, 2014). "Moreover, the inverse correlation between miR-492 and resistin in insulin resistance 3T3-L1 adipocytes consolidated their regulatory relationship in HUVEC cells." (PMID 24526524, 2014). "Previous animal studies, have suggested that resistin may play an important role in the pathogenesis of insulin resistance." (PMID 24414038, 2014). "Furthermore, MIF also stimulates the production of certain inflammatory adipocytokines, such as resistin and IL-6, which are key molecules in the development of insulin resistance." (PMID 24527464, 2014). "Although resistin was firstly postulated to contribute to insulin resistance, more and more evidence indicated that it may also be involved in inflammatory process." (PMID 24692844, 2014). "Additionally, we showed that MIF is important to the production of some adipocytokines such as resistin, which is the most important adipocytokine in the development of insulin resistance." (PMID 24527464, 2014). "For both of the adipokines; serum resistin and plasma leptin (markers of insulin resistance), there was a significant decrease within the intervention group, but this was not significant compared to the control group, where there also was a (non-significant) decrease." (PMID 25330848, 2014). "Moreover, more evidence suggests a role of resistin in the etiology of both insulin resistance and type 2 diabetes mellitus." (PMID 24511320, 2014). "A possible link exist between decreased adiponectin with increased insulin resistance, while some evidence links increased TNF-α and resistin with increased insulin resistance Another study relate higher blood pressures to decreased adiponectin, increased TNF-α, and CRP concentrations." (PMID 24571954, 2014). "Resistin induces insulin resistance, and large amount of resistin is secreted by adipocytes." (PMID 24692844, 2014). "In rats, resistin induces severe hepatic insulin resistance and increases glucose production." (PMID 23772224, 2013). "In the current study, we chose C2C12 myotubes as a cell culture model to test whether resistin can induce insulin resistance in muscle cells." (PMID 23509781, 2013).
Insulin resistance (continued). "The increased third trimester resistin levels, along with other placental-derived hormones, might contribute to the insulin resistance and postprandial hyperglycemia in the second half of pregnancy." (PMID 23691290, 2013). "Some evidence provides linking resistin and RBP4 with insulin resistance or cardiovascular risk." (PMID 23970879, 2013). "Central resistin administration appears to have a dual effect on metabolic homeostasis, first by acutely inhibiting feeding and second by controlling glucose homeostasis and inducing hepatic insulin resistance." (PMID 23710116, 2013). "Therefore, resistin is clearly an important adipokine that likely plays a role in the development of insulin resistance." (PMID 23497617, 2013). "A novel observation amongst models of fetal overnutrition is that the female offspring showed a raised serum IL-6 concentration as young animals compared to controls, and a reduction in resistin, implicating these adipokines in development of insulin resistance." (PMID 23423541, 2013). "The detection of a high resistin expression in immune cells implies that it could possibly play a role in the establishment of insulin resistance through effects on inflammation." (PMID 23691290, 2013). "Visceral adipose tissue is believed to play a pivotal role in the pathogenesis of NAFLD, since it participates in producing most adipokines, such as Tumor Necrosis Factor alpha (TNF-alpha), resistin, and adiponectin, which are involved in inducing insulin resistance and low-grade inflammation." (PMID 23530957, 2013). "In human studies the role of resistin in insulin resistance and glucose metabolism is inconclusive." (PMID 23772224, 2013). "Although resistin was initially suggested to promote insulin resistance and adipocyte differentiation, recent data indicate that this hormone also plays a pleiotropic role in rodents, immunity, food intake, gonadal function, and hypothalamic and peripheral lipid metabolism regulation." (PMID 23710116, 2013). "Although resistin seems not highly correlated to insulin resistance in human, it plays an important role in DM-associated inflammatory reactions." (PMID 24527264, 2012). "However, available data regarding the relationship of serum resistin with BMI and insulin resistance are conflicting." (PMID 22969799, 2012). "Furthermore, an increase in serum resistin levels induced insulin resistance in several rat and mouse models, including after acute administration." (PMID 22110480, 2012). "Salivary resistin may be used as a tool to evaluate insulin resistance and inflammatory state for T2DM patients." (PMID 22969799, 2012). "Increasing evidence indicates that resistin might play important regulatory roles apart from its role in insulin resistance and diabetes, in a variety of biological processes such as atherosclerosis and cardiovascular diseases." (PMID 22910888, 2012). "On regression analyses, changes in BMI predicted changes in insulin (B = 4.9 ± 2, p = 0.03), insulin resistance (B = 1.75 ± 0.65, p = 0.02) and leptin (B = 2.2 ± 1, p = 0.046) but not on ghrelin (B = 38 ± 72, p = 0.61), adiponectin (B = -0.02 ± 1, p = 0.98) or resistin (B = -0.09 ± 0.25, p = 0.74)." (PMID 21676224, 2011). "However, the blood circulating levels of resistin have been shown to be up-regulated in subjects with insulin resistance, T2DM, MS, and cardiovascular disease." (PMID 21251282, 2011). "Taking these studies together, adiponectin and resistin may be useful markers for insulin resistance and the variables that can integrate the abnormalities of the metabolic syndrome and cardiometabolic function." (PMID 21251282, 2011). "The TZD drug rosiglitazone can reduce resistin expression to improve insulin resistance." (PMID 20953398, 2011). "Interestingly, it has been observed that insulin seems to inhibit resistin secretion, while resistin induces insulin resistance, in an insulin-resistin-insulin sensitivity positive feedback loop." (PMID 21760816, 2011).
Insulin resistance (continued). "Regarded initially as markers mainly related to weight regulation and insulin resistance, it has become clear that hormones like leptin, resistin or adiponectin are involved in a variety of functions and diseases, including cardiovascular disease, diabetes and inflammatory diseases." (PMID 21691545, 2010). "Therefore, elevated levels of serum resistin appear to be directly related to insulin resistance in mice." (PMID 20300528, 2010). "This abundance of nonadipose tissue sites for resistin expression has complicated the original hypothesis that resistin might be an important link between adipocytes and insulin resistance." (PMID 21029428, 2010). "For the total patient cohort, serum resistin was correlated to insulin resistance as calculated by the HOMA-IR (homeostasis model assessment for insulin resistance) index and inversely correlated with glucose and insulin at admittance prior to intensive care interventions." (PMID 19545363, 2009). "However, serum resistin was positively correlated with the HOMA-IR as a marker of insulin resistance." (PMID 19545363, 2009). "The mechanisms of insulin resistance in critically ill patients are not well understood; resistin might possibly act as a link between acute inflammation and altered metabolic homeostasis." (PMID 19545363, 2009). "While cytokines like TNF–alfa and IL1 have a profibrotic effect and determine insulin resistance, adipocyte hormones have an opposite result;leptin and visfatin improve insulin resistance, while adiponectin and resistin increase it and have an anti–fibrosis effect." (PMID 20108479, 2008). "TNFα, and resistin have minor relevance as predictors of stress dependent insulin resistance." (PMID 19087258, 2008). "In both studies, a higher signal was found in abdominal WAT suggesting that, similar to rodents, resistin may connect central obesity to insulin resistance and diabetes in man." (PMID 17183659, 2006). "Interestingly, the peak in TNFα and IL-6 levels after LPS administration to humans precedes a phase of prolonged insulin resistance that begins approximately 6 h after LPS administration, closely approximating the time course of resistin induction." (PMID 15578112, 2004). "Furthermore, the chronic state of inflammation, characterized by increased levels of C-reactive protein, inflammatory cytokines, resistin, leptin, and adiponectin, affects insulin resistance, leading to the exhaustion of pancreatic beta cells and impairing the maintenance of normoglycemia." (PMID 40299945, 2025). "In addition to leptin dysregulation, several other contributors—including insulin resistance, mitochondrial dysfunction, oxidative stress, proinflammatory adipokines such as MCP-1 and resistin, and gut microbiota-derived endotoxins—are implicated in driving peripheral and central inflammation." (PMID 40521397, 2025). "Reducing resistin activity may help alleviate chronic inflammation and insulin resistance." (PMID 40869389, 2025). "Here, we tested whether and how the endocannabinoid system (ECS) control circulating peripheral blood mononuclear cells (PBMCs) that produce resistin and infiltrate into the adipose tissue, heart, skeletal muscle, and liver, resulting in inflammation and insulin resistance." (PMID 39050819, 2024). "Although resistin decrease was not significant in the first 3 months, it was evident at 1 year and was directly related to weight loss and Homeostatic Model Assessment for Insulin Resistance (HOMA-IR) index in, being more significant in the OAGB group." (PMID 38833355, 2024). "Furthermore, Lactococcus lactis lowered the respiratory exchanges ratio, increased night cycle activity, increased serum gastric inhibitory polypeptide (GIP) which stimulates insulin production, and lowered resistin, the adipose tissue hormone that is a biomarker of insulin resistance." (PMID 37763997, 2023).
Insulin resistance (continued). "Thus, the SIRD group with high resistin levels may have a relatively high inflammatory state in addition to insulin resistance." (PMID 34996484, 2022). "Specifically, adiponectin and resistin may play a role in insulin resistance." (PMID 35698449, 2022). "Furthermore, steviol inhibited the expression of the resistin gene, which may attenuate insulin resistance in hypertrophied cells." (PMID 36297315, 2022). "In addition, a study revealed that by expressing resistin, osteoclasts induce insulin resistance and suggest that suppression of osteoclasts generation could be a potential therapeutic strategy for insulin resistance." (PMID 36497201, 2022). "According to these data, we hypothesize that palmitic acid or saturated FFAs effects regarding inflammation and insulin resistance could be, at least partially, indirect through the augmentation of resistin plasma levels promoting then neuro-inflammation and overall inflammation." (PMID 33686181, 2021). "Thus, resistin plays an important role in the development of insulin resistance." (PMID 33705641, 2021). "This might be because, unlike in adipocytes, muscle is not a source of resistin, an adipocyte hormone that may mediate or promote the effect of homocysteine in causing adipocyte insulin resistance." (PMID 33400857, 2021). "Thus, the role of resistin in inducing insulin resistance is controversial in humans." (PMID 34680059, 2021). "Indeed, resistin has been identified as proinflammatory and insulin resistance promoting factor." (PMID 33686181, 2021). "Other adipokines, such as resistin, seem to be involved in insulin resistance, while tumor necrosis factor alfa (TNF-α) and IL-6, which may be present at early and late stages of NAFLD, increase expression of SREBP-1c in the liver and further promote insulin resistance." (PMID 34950104, 2021). "Importantly, beyond adiposity indexes and insulin resistance, circulating concentrations of resistin (the adipocytokine expressed primarily in monocytes and macrophages, and which responds to inflammatory stimuli) predict the progression to heart failure and its prognosis." (PMID 32000666, 2020). "Moreover, elevated resistin levels were observed to induce insulin resistance in several rat and mouse models, suggesting an involvement of hyper-resistinemia in insulin resistance." (PMID 33192583, 2020). "FGF23 is positively associated with resistin, an adipokine, and regulator of insulin resistance, irrespective of kidney function; it should be further addressed whether this relationship is key to FGF23-induced insulin resistance." (PMID 32857288, 2020). "In addition, considering about the distribution of resistin in mononuclear cells in humans, inflammation might be the process which links resistin to insulin resistance." (PMID 31803062, 2019). "It is still unclear whether resistin promotes insulin resistance in humans." (PMID 31208019, 2019). "Also, the increase in resistin in adult KO mice could contribute to hepatic insulin resistance and increased gluconeogenesis leading to fatty liver disease in adult KO mice." (PMID 31349725, 2019). "Therefore, we hypothesized that resistin might also play a role in insulin resistance, possibly providing new therapeutic targets for the treatment and prevention of diabetes." (PMID 31803062, 2019). "However, the role of resistin in insulin resistance remains controversial in humans." (PMID 31803062, 2019). "This is interesting since these pathways lead to increases in inflammatory cytokines, and as such could provide a further mechanism through which resistin could induce insulin resistance in the brain Any inflammatory processes initiated by high fat feeding could further add to these mechanisms." (PMID 30804811, 2019). "A new therapy to reduce resistin levels may alleviate insulin resistance in the future." (PMID 31803062, 2019).
Insulin resistance (continued). "First, as a cross-sectional study, we could not examine the causative relationships of resistin, vaspin and visfatin with atherosclerosis or insulin resistance." (PMID 29848323, 2018). "Hence, we hypothesized that s-resistin could have an essential role in the hypothalamic function and in the development of central insulin resistance throughout modulation of the inflammatory response." (PMID 29500410, 2018). "Here, we also found that s-resistin expression is increased in 24-month-old Wistar rats, which have been considered as a pre-diabetic model with central leptin and insulin resistance accompanied by peripheral insulin resistance, hyperlipidemia and increased adiposity." (PMID 29500410, 2018). "Since resistin and TNF-α are pro-inflammatory in action, and inflammation has a central role in cardiovascular diseases and insulin resistance, deficiency of vitamin B12 may, therefore, have importance in the development of cardiometabolic diseases in Saudi population." (PMID 27608037, 2016). "Thus, our data suggest that resistin may be a link between thyroid dysfunction and insulin resistance and at least serve as a biomarker for insulin resistance and probably other diseases." (PMID 27193069, 2016). "Finally, according to the results of in vitro experiments, a positive relationship between resistin and cortisol could be presumed, corresponding to the supposition that resistin was involved in glucocorticoid-induced insulin resistance." (PMID 25129652, 2015). "Specifically, because of higher predicted prevalence of overweight and obesity and higher insulin resistance, we hypothesized that older US and Italian children would have higher BMIs, lower adiponectin, and higher resistin compared to Japanese and Thai children." (PMID 25904939, 2015). "Therefore the involvement of resistin in insulin resistance needs to be confirmed." (PMID 24695544, 2014). "They reported that insulin resistance in acromegaly may be due to other reasons than resistin." (PMID 23533949, 2013). "In a word, resistin could induce hepatic insulin resistance by inhibiting the phosphorylation of Akt and GSK3, and its effect on insulin sensitivity is opposite to those reported for the adipocyte-secreted hormone adiponectin, which increases insulin sensitivity of the same liver-specific functions." (PMID 23762871, 2013). "Indeed, in patients with very low 25(OH)D levels, we found higher levels of the inflammatory marker hsCRP, and of resistin, which is also considered as an inflammatory marker in human, in addition to its promoting role on insulin resistance and cardiovascular diseases." (PMID 24058636, 2013). "Therefore, resistin may have an indirect effect on insulin resistance in humans through exacerbating inflammation, which has been shown to disturb insulin sensitivity." (PMID 24455420, 2013). "Thus, resistin plays an important role in inflammation as well as insulin resistance." (PMID 21912448, 2011). "A recent clinical trial revealed pioglitazone plus vildagliptin treatment improved both adiponectin and resistin levels and might effective in preserving beta-cell function, and in reducing insulin resistance and inflammatory state parameters in subjects with poorly controlled T2DM." (PMID 21251282, 2011). "The role of resistin in insulin resistance and diabetes is controversial since a number of studies have shown that resistin levels increase with increased central adiposity and other studies have demonstrated a significant decrease in resistin levels in increased adiposity." (PMID 20634940, 2010). "A recent study, using a novel 'humanized resistin mouse' model that lacks adipocyte-produced mouse resistin but expresses human resistin derived from macrophages, could show that macrophage-derived human resistin contributes to insulin resistance by means of its inflammatory properties." (PMID 19545363, 2009).